BCL2 (BCL2 apoptosis regulator)
Diseases named in the same sentence as BCL2 in open-access papers (continued):
Sharing a sentence is not in itself a finding about the gene and the disease.
AIDS (2 papers, 2011 to 2020). A syndrome resulting from the acquired deficiency of cellular immunity caused by the human immunodeficiency virus (HIV). "Increased serum/plasma levels of molecules involved in B-cell activation, among which soluble (s)CD23, sCD27, sCD30, sCD44, and CXCL13, have been associated with the development of acquired immune deficiency syndrome (AIDS)-related BCL2–7." (PMID 32796953, 2020). "Since either Tat or FGF-2 has been shown to modulate Bcl-2 expression by a wide variety of cell types, herein we evaluated the effects of FGF-2 and Tat, alone or combined, on Bcl-2 expression in animal and in vitro experimental models previously employed to study AIDS-KS pathogenesis." (PMID 22007303, 2011). "Here, we evaluated whether FGF-2 or HIV-1 Tat, two key AIDS-KS pathogenetic factors, could affect Bcl-2 expression in vivo and in vitro." (PMID 22007303, 2011).
anal tumours (2 papers, 2010 to 2015). "Moreover, the Bax/Bcl-2 ratio was significantly lower in tumors resected from colon compared to sigmoid colon, rectosigmoid and rectum tumors." (PMID 25864810, 2015).
anxiety disorder (2 papers, 2012 to 2025). A category of psychiatric disorders which are characterized by anxious feelings or fear often accompanied by physical symptoms associated with anxiety. "BAX and BCL-2 are critical proteins involved in the regulation of apoptosis, and their roles in anxiety disorders have garnered increasing attention in recent years." (PMID 40509387, 2025).
asthenozoospermia (2 papers, 2024 to 2025). "ULA has been reported that has a protective effect on LPS-Induced asthenozoospermia via Bcl-2/Bax apoptosis signaling pathway." (PMID 38978752, 2024). "Thus, in oligoasthenozoospermia, Acorus tatarinowii alleviates asthenozoospermia symptoms effectively through modulation of the BCL2/Bax/Caspase3 pathway." (PMID 39828700, 2025).
atrial fibrillation (2 papers, 2013 to 2026). A disorder characterized by an electrocardiographic finding of a supraventricular arrhythmia characterized by the replacement of consistent P waves by rapid oscillations or fibrillatory waves that vary in size, shape and timing and are accompanied by an irregular ventricular response. "This study investigated the effects of high-intensity interval training (HIIT) and moderate aerobic training (AT) on FGF23, Klotho, mineral metabolism, apoptosis markers (BAX, Bcl2), and atrial fibrillation (AF) in a rat CKD model." (PMID 42072635, 2026). "We measured heart weight, blood levels of FGF23, Klotho, and mineral metabolism markers, as well as the heart expression of apoptosis proteins (i.e., BAX, Bcl2) and atrial fibrillation (AF)." (PMID 42072635, 2026).
benign cystadenomas (2 papers, 2009 to 2023). "Stromal Bcl-2 intensity in cystadenomas was significantly different versus intensity in MD and PD specimens (P = 0.003 and P < 0.0001, respectively), while stromal Bcl-2 intensity in cysts was not significantly different from any of the specimens." (PMID 19852858, 2009).
benign salivary gland neoplasm (2 papers, 2008 to 2012). "Bcl-2 was detected only in three of the malignant, but in six of the benign salivary gland tumours." (PMID 18840281, 2008).
brain haemorrhages (2 papers, 2009 to 2015). "The induction of intracranial hemorrhage suppresses the expression of Bcl-2 and increases the expression of Bax, resulting in an increase of the Bax to Bcl-2 ratio." (PMID 25891426, 2015). "Significantly, Bcl-2-transgenic mice developed more severe disease that was dependent on neutrophils, characterized by pronounced vasogenic edema, vasculitis, brain haemorrhages and higher clinical scores." (PMID 19478887, 2009).
C. perfringens infection (2 papers, 2020 to 2025). "Our results showed that C. perfringens infection elevated Caspase-3 and Bax levels and increased the Bax/Bcl-2 ratio, indicating apoptosis in the ileal mucosa." (PMID 40427288, 2025). "C. perfringens infection significantly decreased the number of Bcl-2-positive cells, while probiotic treatment alleviated the decrease." (PMID 33679724, 2020). "C. perfringens infection significantly increased the expression of pro-apoptotic proteins Bax and Caspase-3, as well as the Bax/Bcl-2 ratio (p < 0.05), and decreased the expression of anti-apoptotic Bcl-2." (PMID 40427288, 2025).
Cachexia (2 papers, 2022 to 2024). Severe weight loss, wasting of muscle, loss of appetite, and general debility related to a chronic disease. "Based on these findings, we propose that ACT may exert its anti-cachexia effects through the regulation of inflammatory response and energy metabolism via multiple targets, including CYP3A4, CYP19A1, CYP2E1, TNF, BCL-2, RYR2, and ATP2A1." (PMID 39872045, 2024).
cerebral (2 papers, 2014 to 2025). "The mitochondrial apoptotic pathway plays an important role in neuronal injury, and sevoflurane inhibits cellular apoptosis after brain cerebral ischemic injury by upregulating Bcl-2 expression and reducing Bax expression." (PMID 24614080, 2014).
cerebral aneurysm (2 papers, 2017 to 2021). "Especially, we further observed participation of BCL-2-mediated apoptosis pathway and caspase-1 related pyroptosis in the development of cerebral aneurysm and aneurysmal subarachnoid hemorrhage in corresponding transcriptomes." (PMID 34895131, 2021). "CaCl2‐induced cerebral aneurysm had reduced bax expression and increased bcl‐2 expression." (PMID 28948066, 2017).
cervical intraepithelial neoplasia (2 papers, 2015 to 2022). "An increase in Bcl-2 protein expression as demonstrated in this study is in accordance with the results of Dimitrakakis and colleagues where it was shown that Bcl-2 protein expression is directly related to the grade of cervical intraepithelial neoplasia." (PMID 26474854, 2015). "published a study on BCL2 gene polymorphism and cervical intraepithelial neoplasia (CIN), and found that rs2279115 SNP is not significantly related to CIN, but confirmed that the promoter SNP rs2279115 is related to elevated BCL2 protein expression." (PMID 35814404, 2022).
childhood cancer (2 papers, 2019 to 2025). "Intriguingly, despite the development of another BH3 mimetic Obatoclax (GX15-070), which can also target MCL-1 in addition to BCL-2 and BCL-XL, and with its efficacy tested in various adult cancers, its effectiveness in childhood cancers was, nevertheless, not well-studied." (PMID 31652776, 2019).
classical Hodgkin lymphoma (2 papers, 2014 to 2025). "Immunohistochemistry showed positivity for CD45, CD20, and EMA and negativity for CD30, CD15, and Bcl-2, excluding alternative diagnoses such as nodular lymphocyte-predominant Hodgkin lymphoma (NLPHL) and classical Hodgkin lymphoma (cHL)." (PMID 40026533, 2025).
diabetic neuropathy (2 papers, 2020 to 2023). A chronic, pathological complication associated with diabetes mellitus, where nerve damages are incurred due to diabetic microvascular injury involving small blood vessels that supply these nerves, resulting in peripheral and/or autonomic nerve dysfunction. "This confirmed the apoptosis effect of the Bax/Bcl-2 ratio and caspase-3 in the diabetic neuropathy rats." (PMID 38004451, 2023). "It is also reported in the present study that lowering the expression of Bax and the ratio between Bax/BCl2 with the treatment of R. cordifolia reverses diabetic neuropathy in rats." (PMID 38004451, 2023).
duodenal ulcer (2 papers, 2014 to 2023). An ulcer in the duodenal wall. "Our invivo data confirm that DSW ingestion attenuates the area of acetic acid-induced duodenal ulcers and apoptosis numbers via the action of selenium to induce Bcl-2 and Txnrd1 expression." (PMID 24984066, 2014). "Bax/Bcl-2/caspase 3/poly-(ADP-ribose)-polymerase signaling was activated during the pathogenesis of duodenal ulceration." (PMID 24984066, 2014). "Our data indicate that DSW or selenium ingestion increases duodenal Trxnrd1 and Bcl-2 protein expression and inhibits apoptosis signaling and number in acetic acid-induced duodenal ulcer." (PMID 24984066, 2014). "We hypothesized that Bax/Bcl-2/caspase 3/PARP signaling may be involved in the pathogenesis of duodenal ulceration." (PMID 24984066, 2014). "We confirm that activated Bax/Bcl-2 ratio, caspase 3, and PARP signaling contributes to acetic acid-induced duodenal ulceration." (PMID 24984066, 2014).
Ehrlich tumor (2 papers, 2019 to 2023).
Endometrial Cyst (2 papers, 2020 to 2024). It is caused by endometriosis, and formed when a tiny patch of endometrial tissue (the mucous membrane that makes up the inner layer of the uterine wall) bleeds, sloughs off, becomes transplanted, and grows and enlarges inside the ovaries. "Furthermore, the increase of PGE2 can promote the development of endometrial cysts through apoptosis inhibition by increasing the anti-apoptotic protein Bcl2 and reducing the pro-apoptotic protein Bax." (PMID 32685413, 2020).
endometrioid adenocarcinoma (2 papers, 2021 to 2022). An adenocarcinoma characterized by the presence of malignant glandular epithelial cells resembling endometrial cells. "In our study, the A cases associated with G2 endometrioid carcinoma and hyperplastic transformations were positive for BCL-2." (PMID 35628423, 2022).
ependymoma (2 papers, 2017 to 2019). A WHO grade II, slow growing tumor of children and young adults, usually located intraventricularly. "LINC00899 knockdown in spinal ependymoma cells elevated levels of RBL2, p21, p27 and Bax; decreased levels of FoxO, Bcl-2, vimentin and annexin; reduced cell proliferation, migration and invasion; and enhanced apoptosis." (PMID 31739288, 2019).
Fibrous Tumor (2 papers, 2014). "After a tumor resection, microscopic findings were spindled tumor cells with reactivity to CD34, bcl-2 and CD99 and the tumor was diagnosed as Solitary Fibrous Tumor." (PMID 25136435, 2014). "Solitary fibrous tumor is rich in collagen and, differently from GPC, tumor cells are positive to bcl-2 and negative to CD34 and actin." (PMID 25143851, 2014).
folate deficiency (2 papers, 2015 to 2023). A nutritional condition produced by a deficiency of FOLIC ACID in the diet. "The experimental findings suggested that reduced anti-apoptotic protein Bcl-2 expression and improved pro-apoptotic protein Bax expression via by parental folate deficiency were observed in pups’ hippocampus and cerebral cortex neural cells." (PMID 37833955, 2023). "The impacts of both maternal and paternal folate deficiency on the expression of Bcl-2 and Bax in offspring’s neurons were greatest together and greater unilaterally in the maternal generation than in the paternal generation." (PMID 37833955, 2023).
fragile X syndrome (2 papers, 2013 to 2022). A genetic syndrome caused by mutations in the FMR1 gene which is responsible for the expression of the fragile X mental retardation 1 protein. "This set of genes included cancer oncogenes (CMYC, CKIT, BCL2, KRAS) and genes associated with different cancer types (ADAM12, ALOX5, SRSF6, VEGF12) as well as FMR1, associated with fragile X syndrome (OMIM: 300624), and SNX12, which is associated with neurodegenerative diseases." (PMID 35573091, 2022).
glomus tumor (2 papers, 2013 to 2018). A rare benign or malignant mesenchymal neoplasm arising from cells that resemble the modified smooth muscle cells of the glomus body.
Glucose intolerance (2 papers, 2017 to 2022). Glucose intolerance (GI) can be defined as dysglycemia that comprises both prediabetes and diabetes. "They generated mutant mice (BCL2 phosphorylation mutation) presenting decrease of endurance to exercise and altered glucose metabolism during acute exercise, as well as impaired chronic exercise-mediated protection against high-fat-diet-induced glucose intolerance." (PMID 28255159, 2017). "Mice that are defective in stimulus-induced autophagy due to knock-in mutations in BCL2 phosphorylation sites (T69A, S70A and S84A) (Bcl2 AAA mice) also showed impaired exercise-mediated protection against glucose intolerance after HFD." (PMID 35237600, 2022).
gout (2 papers, 2021 to 2022). A condition characterized by painful swelling of the joints, which is caused by deposition of urate crystals. "Compared with normal mice, the mRNA expression levels of IL-6 and Bcl2 were significantly increased in hyperuricemic-gout mice." (PMID 35672755, 2022). "Furthermore, Simiao powder certainly regulates the expression of PPAR-γ, PTGS1, IL-6 and Bcl2 mRNA in ankle tissue in hyperuricemic-gout mice." (PMID 35672755, 2022). "In addition, the main characteristic chemical components of Simiao Powder have good binding ability with IL-6, PTGS1, PPARG and BCL2 targets, which indicates that the active components of Simiao Powder can effectively treat gout by combining with core targets." (PMID 35672755, 2022). "In addition, our experiments showed that Simiao powder certainly regulates the expression of PPAR-γ, PTGS1, IL-6 and Bcl2 mRNA in ankle tissue in hyperuricemic-gout mice." (PMID 35672755, 2022). "Moreover, gout patients indicated low anti-apoptotic target proteins (Bcl-2, Bcl-XL) in synovial T cells, which is clear evidence of immunocompromised condition during gouty arthritis." (PMID 34502281, 2021).
Granuloma (2 papers, 2018 to 2023). A compact, organized collection of mature mononuclear phagocytes, which may be but is not necessarily accompanied by accessory features such as necrosis. "We show that specifically inhibiting MCL-1 and BCL-2 induces apoptosis of M.tb-infected macrophages, and markedly reduces M.tb growth in human and murine macrophages, and in a pre-clinical model of human granulomas." (PMID 37864894, 2023). "Thus, we believe that our results that specific inhibition of MCL-1 plus BCL-2 reduces M.tb growth in a human granuloma model indicate that this is a potentially promising approach for TB treatment." (PMID 37864894, 2023). "Excitingly, we found that inhibition of BCL-2 with the FDA approved ABT-199 along with MCL-1 inhibition with inhibitors in clinical trials and in the preclinical stage, significantly limits M.tb growth in human and murine macrophages, and a pre-clinical human granuloma model." (PMID 37864894, 2023).
Hematochezia (2 papers, 2021 to 2025). The passage of fresh (red) blood per anus, usually in or with stools. "After starting oral Bcl-2 inhibitor venetoclax, the results of peripheral hemogram and the body temperature gradually turned normal, with no symptoms of hematochezia occurring again." (PMID 40666527, 2025).
hepatitis C (2 papers, 2020 to 2023). "The top five degrees of the potential targets for the YCHD in the treatment of hepatitis C include PIK3CG, CASP3, BCL2, CASP8, and MMP1." (PMID 32050950, 2020).
hippocampal atrophy (2 papers, 2015 to 2025). "In AD mice, CSCPs-NPs significantly improved cognitive function and motor coordination, reduced hippocampal atrophy, preserved neurons, and mitigated oxidative stress, neuroinflammation, and apoptosis (upregulated Bcl-2, downregulated Bax)—effects matching high-dose free CSCPs." (PMID 41440906, 2025).
histiocytic neoplasm (2 papers, 2018 to 2025). Histiocytic tumors are a heterogeneous group of tumors and tumorlike masses commonly associated with histologically identical extracranial lesions.
hydatidiform mole (2 papers, 2013 to 2015). A gestational trophoblastic disorder characterized by marked enlargement of the chorionic villi, hyperplasia of the villous trophoblastic cells and hydropic changes. "Based on the calculation of immunoexpression total score, the total score average of Bcl-2 immunoexpression for complete hydatidiform mole is 2.36, weaker than normal placenta which shows strong Bcl-2 expression (total score average is 6)." (PMID 26494988, 2015).
hyperhomocysteinemia (2 papers, 2013 to 2020). A serious metabolic condition caused by mutations in the MTHFR gene, medications, or nutritional deficiency. "It has been reported that hyperhomocysteinemia causes increase in pro-apoptotic Bax levels and decrease in anti-apoptotic Bcl-2 levels in the rat brain." (PMID 24551795, 2013). "This study was performed to evaluate the effects of excess methionine on growth performance, serum homocysteine levels, apoptotic rates, and Bax and Bcl-2 protein levels in geese and to study the role of betaine in relieving excess Met-induced hyperhomocysteinemia." (PMID 32932584, 2020). "The objective of our study was to investigate the effects of excess Methionine (Met) on the growth performance, serum homocysteine levels, apoptotic rates, and Bax and Bcl-2 protein levels in geese and to study the role of Bet (betaine) in relieving excess Met-induced hyperhomocysteinemia (HHcy)." (PMID 32932584, 2020).
hypertensive renal disease (2 papers, 2017 to 2024). "One such example is that of BCL2 and its associations with both lymphocyte count, and hypertensive renal disease, as murine knockout of Bcl2 reports lymphoid and kidney development effects." (PMID 38589365, 2024). "Meanwhile ICV injection of losartan, FTS, and PD98059 in rats with renal hypertension significantly reduced Bax amounts, and markedly increased Bcl-2 levels." (PMID 28210225, 2017).
Hypoxic-Ischemic Encephalopathy (2 papers, 2016 to 2020). "In addition, DIM inhibited apoptosis and oxidative stress accompanying perinatal asphyxia through: downregulation of FAS, CASP-3, CAPN1, GPx3 and SOD-1, attenuation of caspase-9 activity, and upregulation of anti-apoptotic Bcl2 mRNA." (PMID 32816128, 2020).
interstitial lung disease (2 papers, 2021 to 2023). A diverse group of lung diseases that affect the lung parenchyma. "There is a growing body of evidence that suggests a crucial role for Bcl-2 in the pathogenesis of inflammation, apoptosis and fibrosis induced by various factors in the interstitial lung diseases." (PMID 34692765, 2021). "STAT family of proteins can activate the expression of many survival-related genes, including BCL2, HIF-α, VEGF and IL-6, that play an important role in interstitial lung diseases via stimulating survival, proliferation, angiogenesis and migration and resisting autophagy." (PMID 37242480, 2023).